FOXP3 (forkhead box P3)
Diseases named in the same sentence as FOXP3 in open-access papers (continued):
Sharing a sentence is not in itself a finding about the gene and the disease.
neuroblastoma (7 papers, 2014 to 2021). Neuroblastoma (NB) is the most common solid, extracranial childhood tumor. "It has been reported previously that human neuroblastoma tumors have a fairly substantial FoxP3+ cell infiltration of between 40 and 55% of CD4+ cells, however this was only demonstrated in a small cohort of 3 patients." (PMID 33028899, 2020). "Thus, the present study aimed to examine the expression of CXCR4 and Foxp3 in neuroblastoma cell lines LAN-5 and SK-N-SH." (PMID 24932293, 2014). "Although the abnormal expression of CXCR4 and Foxp3 may be involved in the metastasis and immune evasion of other types of tumors, their role in neuroblastoma and their response to chemotherapy remain largely unclear." (PMID 24932293, 2014). "In conclusion, the present study demonstrates that CXCR4 and Foxp3 exhibit higher expression in neuroblastoma cells, and therefore, exposure to chemotherapy agents may reduce their expression." (PMID 24932293, 2014). "In addition, the results suggest that CXCR4 and Foxp3 may present as potential targets for neuroblastoma chemotherapy." (PMID 24932293, 2014). "It is worth mentioning that, in neuroblastoma, the two cases with strongest CD8 and CD45RO density z‐score presented mid/low range PD‐L1 z‐scores; while the two cases with highest FoxP3 density z‐scores shown low PD‐L1 z‐scores." (PMID 31922656, 2020). "The present study aimed to examine the expression of CXCR4 and Foxp3 in the LAN-5 and SK-N-SH neuroblastoma cell lines." (PMID 24932293, 2014). "However, the role of Foxp3 in neuroblastoma is largely unknown." (PMID 24932293, 2014). "In this study, the expression of Foxp3 in neuroblastoma cells was investigated and our findings indicated that Foxp3 was expressed in the LAN-5 and SK-N-SH neuroblastoma cell lines." (PMID 24932293, 2014). "Therefore, the high expression of CXCR4 and Foxp3 in LAN-5 and SK-N-SH cells and their subsequent downregulation following administration of the chemotherapy agents suggests that the chemokine receptors, CXCR4 and Foxp3, may be involved in the metastasis and tumor evasion of neuroblastoma." (PMID 24932293, 2014). "Previously, we showed that the PD-1 expression on CD3 T cells surged around day 16 after GD2-BsAb treatment was started, while the neuroblastoma PDXs harvested on day 10 post-treatment had few FoxP3+ Tregs irrespective of treatment." (PMID 34496935, 2021). "In our study, Foxp3 and CXCR4 were expressed in neuroblastoma cells; therefore, it may be possible that Foxp3 expressed in these cells upregulated CXCR4 and contributed to the higher frequency of neuroblastoma." (PMID 24932293, 2014).
Pleural effusion (7 papers, 2015 to 2024). The presence of an excessive amount of fluid in the pleural cavity. "The frequency of CD4+IL-9+, CD4+IL-17+, CD4+ IL-22+, and CD4+CD25+FOXP3+ cells in the pleural effusions." (PMID 34925358, 2021). "In a comparison of TB pleural effusion and miliary TB, representing in this case containment vs. dissemination of disease, elevated FOXP3 mRNA expression levels and frequencies of CD4+Foxp3+CD25+ T-cells were found in cells isolated from miliary disease sites." (PMID 26029205, 2015). "CD8+, CD4+, and CD4+/FoxP3+ T-cells are present in the majority of patients, but the number of T-reg cells in pleural effusions of MPM patients is lower than in other solid tumors, confirming the presence of an immunosuppressive milieu in MPM tumoral mass, rather than in pleural effusion." (PMID 34073720, 2021). "Moreover, the ascites and pleural effusions had a similar expression rate of PD-1 in Foxp3+ Treg and Foxp3− Tconv cells." (PMID 31801611, 2019). "We also tested the effects of ASO FOXP3 on six Treg depleted samples, two of which were healthy donors PBMC and four were cancer tumors, lymph nodes and pleural effusion." (PMID 39234236, 2024). "Therefore, human cancer Treg (intratumoral, pleural effusion, lymph nodes and even distal tumor-free cancer lungs) were more sensitive to ASO FOXP3, in comparison with peripheral Tregs, at both FOXP3 mRNA and protein levels." (PMID 39234236, 2024).
tongue squamous cell carcinoma (7 papers, 2015 to 2022). A squamous cell carcinoma that arises from the tongue. "In fact, it has been reported that tongue SCC tumor cells express Foxp3 and its expression significantly associated with disease progression and poor patient outcome." (PMID 30460193, 2018). "In this study, we assessed the role of TIL markers (CD3, CD4, CD8, and FOXP3) in a large cohort of patients with pure tongue squamous cell carcinoma receiving maximal curative treatment involving radical surgery and adjuvant RT or adjuvant CCRT." (PMID 30153850, 2018). "The different outcomes of FOXP3 in HPV-positive oropharyngeal cancer and tongue SCC indicate the minor role of microbial-associated pathogenesis in tongue SCC." (PMID 30153850, 2018). "Our previous study revealed the expression of Foxp3 in tongue squamous cell carcinoma (TSCC) cells, and showed that the expression of cancer cell-derived Foxp3 was positively associated with the pathologic differentiation and T stage, and inversely associated with overall survival of TSCC patients." (PMID 25779374, 2015). "In addition, in patients with tongue SCC, the frequency of CD4+CD25+Foxp3+CD127low/− cells was significantly lower in TDLNs of LN+ patients (patients with at least one involved LN) in comparison with LN– ones (patients without involved LN, P = 0.036)." (PMID 36376825, 2022). "Our study demonstrated that in tongue squamous cell carcinoma, higher CD4 infiltration and higher CD4/CD3, CD4/CD8, and CD4/FOXP3 ratios were associated with the absence of LVI, indicating the role of CD4 TILs in the prevention of early metastatic invasion." (PMID 30153850, 2018).
autoimmune uveitis (6 papers, 2012 to 2022). An autoimmune form of uveitis (disease). "We next asked if the Treg subset that was previously identified in mice that suppresses autoimmune uveitis as PD-1+FoxP3+CD25+CD4+ 15 can be induced through stimulation of the melanocortin-adenosinergic pathway." (PMID 31729418, 2019). "Interestingly, in 12-week-old eyes with experimental autoimmune uveitis FoxP3 expression in RPE cells was comparable to 11-month-old untreated rats (62, 6%, n = 10)." (PMID 36273134, 2022). "Stat3 deletion in T cells also prevents autoimmune uveitis and EAE and increases the expression of IL10 and forkhead box P3 (FoxP3), and the expression of FoxP3 programs the development and functions of Treg cells." (PMID 22203863, 2012). "Our study demonstrates that zebularine restrains IFN-γ and IL-17 expression and promotes Foxp3 expression in CD4+ T cells and may serve as a candidate therapeutic agent for autoimmune uveitis." (PMID 31475011, 2019).
bladder tumors (6 papers, 2015 to 2025). "A high number of FOXP3‐positive T cells around bladder tumors was associated with a poor response to BCG treatment for NMIBC." (PMID 40084633, 2025). "Our finding that FOXP3-linked genes are associated with poor prognosis in a subset of bladder tumor patients suggests a specific patient subset predicted to benefit from therapeutic reduction of FOXP3+ Tregs." (PMID 26398410, 2015). "We showed that high levels of a gene network including the T regulatory (Treg) gene FOXP3 are associated with poor survival of bladder tumor patients." (PMID 26398410, 2015). "In contrast, FOXP3.mod hi bladder tumors were associated with worse patient survival." (PMID 26398410, 2015). "However, in general, CD45RO+ lymphocytes followed by CD3+ cells were the most frequent subsets in both areas of the bladder tumor tissues, while FOXP3+ cells showed the lowest prevalence." (PMID 36038861, 2022). "We found that patients with high percentages of Foxp3+ T cells in peritumor tissues had higher recurrence rates than did those with low percentages of Foxp3+ T cells after primary transurethral resection of bladder tumor (TURBT)." (PMID 30261082, 2018). "Thirty-three of 145 (22.8 %) bladder tumors exhibit Foxp3 expression." (PMID 27557492, 2016). "Immunohistochemically, thirty-three of 145 (22.8 %) bladder tumors expressed Foxp3 protein." (PMID 27557492, 2016). "Here we show evidence for significant negative association of FOXP3-linked genes and patient survival in only 1/12 tumors tested (bladder tumors)." (PMID 26398410, 2015). "Third, unlike the other study with muscle-invasive bladder cancer, it is lack of correlation of Foxp3 expression with tumor stage or grade in the current cohort of 145 bladder tumors." (PMID 27557492, 2016).
Candida infection (6 papers, 2014 to 2025). "While IL-6 is required for Th17 development and resistance to Candida infection, our data show that elevated levels of IL-6 are strongly associated with Foxp3+ TregDys phenotype and immunopathology in infected aged mice." (PMID 33240286, 2020). "Collectively, these results showed that IL-1β/IL-1R signaling is required for promoting mTOR activation and IL-17A induction in Foxp3+ cells during Candida infection in oral mucosa." (PMID 33240286, 2020). "Interestingly, although SqP tissues also had secondary Candida infection, the numbers of all immune cytokine-producing cells and Foxp3 cells were noticeably lower." (PMID 34209407, 2021). "Our results imply that Candida infection in the context of IL-1β/IL-6 imbalance may lead to an inappropriate accrual of dysfunctional IFN-γ+Foxp3+ cells." (PMID 33240286, 2020). "Thus, our study supports that IL-1β/IL-6 imbalance is central to Foxp3+ cell plasticity and inflammation control during Candida infection." (PMID 33240286, 2020). "Although Treg cells play an important role in immune regulation and tolerance, SqP with Candida infection did not exhibit high numbers of Foxp3+ cells, which may indicate that the immune tolerance mechanism in SqP was different from that of the other tissues." (PMID 34209407, 2021).
chordoma (6 papers, 2020 to 2024). Chordomas are rare malignant tumors arising from embryonic remnants of the notochord in axial skeleton. "Zou analyzed two subtypes of T cells (CD8+ TILs and Foxp3+ TILs) in chordoma in 2018 and found that the ratio of CD8+ TILs to Foxp3+ TILs was 3.3 times and related to the patient’s overall survival (OS)." (PMID 37720221, 2023). "Five chordoma specimens were used for analysis of PD‐1, CD3, CD8, CD20, and Foxp3 expression by both flow cytometry and quantitative immunofluorescence." (PMID 32508056, 2020). "FOXP3 negative CD4+ cells were identified as helper T cells, co-localization of CD4 and FOXP3 in the absence of CD8 identified Tregs, and CD8+ cells were identified as T cells with potential cytotoxic activity against chordoma cells." (PMID 36338744, 2022).
chronic GVHD (6 papers, 2012 to 2023). "Chronic GVHD patients had markedly low percentages of Foxp3+CD4+ regulatory T (Treg) cells in the blood." (PMID 34539630, 2021). "Our chronic GVHD mice showed a robust decrease in the percentage of CD4+CD25+FoxP3+ T cells, which was compromised by an expanded T cell population." (PMID 23116248, 2012). "Treg number measured by CD4+CD25+FoxP3+ staining has been found to be decreased in patients with chronic GVHD." (PMID 23116248, 2012). "Analysis of oral mucosal tissue in patients found that FoxP3+ cells were observed in the basement membrane in acute (small numbers of FoxP3+CD8+ T cells) and chronic GVHD patients, although the origin of these Tregs were not examined." (PMID 35799783, 2022).
cutaneous leishmaniasis (6 papers, 2012 to 2021). Leishmaniasis affecting the skin. "An experimental model of cutaneous leishmaniasis demonstrated that the presence of Foxp3+ Treg cells in the epidermis was associated with a controlled immune response that limited tissue pathology." (PMID 34248935, 2021). "Moreover, skin lesions of patients affected by cutaneous leishmaniasis caused by L. (V.)braziliensis showed a stronger correlation between IL-10 expression and proinflammatory cytokines such as IFN-γ, IL-27, and IL-21, rather than with FoxP3+ cells." (PMID 29743809, 2018). "Taken together, the data obtained in this study suggest that CD4+ T lymphocytes and FoxP3+ T regulatory cells, as well as TGF-β+ and IL-10+ cells, although discrete, play an important role in the immunopathogenesis of nonulcerated or atypical cutaneous leishmaniasis." (PMID 29743809, 2018).
enteritis (6 papers, 2011 to 2024). Inflammation of the small intestine. "The Foxp3 protein content increased significantly, and its content was higher than that of the enteritis group (p<0.05)." (PMID 30364052, 2018). "This study suggests that the transfer of CD4+CD25+ Tregs can stabilize Foxp3 gene expression, which can influence the differentiation of Th17/Tregs, and mouse enteritis was reduced." (PMID 30364052, 2018). "This study examined whether Tregs can affect mouse enteritis and the Foxp3 (Forkhead transcription factor) transcriptional pathway." (PMID 30364052, 2018). "The level of Foxp3 expression significantly increased (p<0.05) compared to the enteritis group." (PMID 30364052, 2018). "The number of CD4+CD25+Foxp3+ Tregs and CD4+IL-17A+ Th17 cells in the mesenteric lymph nodes differed significantly from the enteritis and Tregs-inhibiting groups (p<0.05)." (PMID 30364052, 2018). "Low IL-10 release by peripheral T cells was also detected in a group of non-IPEX patients, without detectable FOXP3 mutation, but with autoimmune manifestations of unknown origin (most of them displayed enteritis) kept under control by multiple immunosuppressive treatments." (PMID 21400500, 2011). "There were more Foxp3+ Tregs and Smad3 and NFAT2 infiltrated into the duodenum after adoptive transfer of CD4+CD25+ Tregs, which was a significant difference relative to the enteritis group (p<0.05)." (PMID 30364052, 2018).
esophageal adenocarcinoma (6 papers, 2018 to 2022). A malignant tumor with glandular differentiation arising predominantly from Barrett mucosa in the lower third of the esophagus. "The number of FoxP3+ T cells in the stroma of esophageal adenocarcinoma correlates with later stage and poor response to therapy, while a large amount of FoxP3 in the stroma of ESCC correlates with a good prognosis." (PMID 34203319, 2021). "Together with the evidence of the positive effect of Foxp3+ Tregs on survival in esophageal adenocarcinoma, the immune microenvironment characteristics of the esophagus needs deep exploration to figure out which factors lead to the difference in the role of Foxp3 + Tregs." (PMID 30285868, 2018).
fibrosis (6 papers, 2014 to 2023). the formation of excess fibrous connective tissue in an organ or tissue in a reparative or reactive process. "We found that both fibrosis and spleen disease were independently associated with high FOXP3+ eTreg levels in the blood." (PMID 26731721, 2016). "Furthermore, the number of liver infiltrating Foxp3+ cells increases with fibrosis and in patients with advanced fibrosis was significantly higher than in F0 and F1 patients." (PMID 31318916, 2019). "We quantified FOXP3+, CD4+, CD8+ and CD20+ cells in liver biopsies of 35 male subjects matched by age and ISHAK fibrosis score, 12 HIV monoinfected, 11 HCV monoinfected and 12 HIV/HCV coinfected." (PMID 24597693, 2014).
glomerulonephritis (6 papers, 2014 to 2021). A renal disorder characterized by damage in the glomeruli. "Regulatory T cells (Tregs) have been shown to play a protective role in glomerulonephritis (GN) and Foxp3 is a master transcription factor in Treg development." (PMID 28469165, 2017). "The CD4+RORγt+FoxP3+ T cells represented intermediates during Tregs/Th17 transdifferentiation, and constituted an independent biofunctional regulatory cell lineage which contributed to cresecentic glomerulonephritis." (PMID 30992023, 2019). "Metformin is a potential new therapy to reduce the levels of IFNγ and increase FOXP3 mRNA expression in SLE and in turn inhibits the development of glomerulonephritis." (PMID 34386197, 2020).
intrahepatic cholangiocarcinoma (6 papers, 2020 to 2024). A carcinoma that arises from the intrahepatic bile duct epithelium in any site of the intrahepatic biliary tree. "The results showed that the average frequency of cells with demethylated FOXP3 in normal tissues was significantly lower than that in tumor tissues from both patients with colorectal cancer (CRC) and intrahepatic cholangiocarcinoma (ICC) rats." (PMID 38331927, 2024). "Lower CD8 T cell density and higher Foxp3 Tregs and immune checkpoint strength in intrahepatic cholangiocarcinoma (ICC) components compared to HCC components may indicate a stronger immune escape capability of ICC." (PMID 34869376, 2021). "The spatial distribution of immune cells in intrahepatic cholangiocarcinoma (iCC) reveals notable patterns: CD8+, CD4+, and CD3+ T cells primarily surround the tumor, while Foxp3+ T cells sometimes infiltrate it." (PMID 39335203, 2024).